KLF4 (KLF transcription factor 4)
Diseases named in the same sentence as KLF4 in open-access papers (continued):
Sharing a sentence is not in itself a finding about the gene and the disease.
glioma (continued). "Interestingly, when ITGB4 levels were increased, it was able to interact with KLF4 and thus decrease its binding to the E3 ligase VHL, leading to its accumulation in glioma." (PMID 30658712, 2019). "In addition, we further analysed the correlation between KLF4 and ITGB4 in human glioma tissues (n = 112)." (PMID 30658712, 2019). "Collectively, our data indicate the existence of a positive feedback loop between KLF4 and ITGB4 that promotes GSC self-renewal and gliomagenesis, suggesting that ITGB4 may be a valuable therapeutic target for glioma." (PMID 30658712, 2019). "Additionally, we also found that knockdown of ITGB4 increased the ubiquitylation of KLF4 in glioma cells, while overexpression of ITGB4 decreased the ubiquitylation of KLF4." (PMID 30658712, 2019). "KLF4 knockdown up-regulated FOXO1 expression at both mRNA and protein levels in glioma cells." (PMID 27835585, 2016). "KLF4 mRNA level significantly increased in the majority of primary glioma tissue samples, compared with matched non-tumor brain tissues." (PMID 27835585, 2016). "Similar to the selective expression of Oct4 and Klf4 in high grade gliomas, mesodermal and endodermal markers were generally absent from grade II tumors." (PMID 21483788, 2011). "They analyzed The Glioma French, the Cancer Genome Atlas (TCGA), and the Chinese Glioma Genome Atlas datasets, reporting that the expression of Twist 1 [a gene that stimulates the stemness markers such as BMI1, CRIPTO1, DPPA2, KLF4, and SOX2 in CSC] is related to a poor prognosis in GB patients." (PMID 39153092, 2024). "However, the regulation of miR-370-5p/KLF4 axis is not the only action mechanism involving CHRM3-AS2 in glioma." (PMID 35359381, 2022). "Further mechanistic studies revealed that KLF4, an important transcription factor, could directly bind to the promoter of ITGB4, facilitating its transcription and contributing to increased ITGB4 expression in glioma." (PMID 30658712, 2019). "Importantly, the negative association between KLF4 and FOXO1 levels was observed in glioma tissue samples." (PMID 27835585, 2016). "While the mRNA levels of genes related to pluripotency (SOX2, KLF4, MYC and NOTCH1) were not obviously correlated with the clinical glioma grade or outcome, the mRNA level of POU5F1, which also plays a crucial role in PGC specification, was often linked to a higher glioma grade and poor outcome." (PMID 36435765, 2022). "These investigations indicated a negative correlation between KLF4 and FOXO1 in gliomas." (PMID 27835585, 2016).
Obesity (39 papers, 2013 to 2025). Accumulation of substantial excess body fat. "In summary, these findings suggest that KLF4 indirectly mediates obesity-associated cardiac injury, controls myocardial remodeling, and confers protection on the heart." (PMID 38516000, 2024). "In the recipient macrophages, miR-34a inhibits M2 polarization by inhibiting the expression of Krüppel-like factor 4 (Klf4), exacerbating systemic inflammation and contributing to the metabolic abnormalities caused by obesity." (PMID 33959041, 2021). "Adipocyte-specific depletion of miR-34a reprograms ATMs from pro-inflammatory M1-like to anti-inflammatory M2-like phenotype and protects mice from obesity-associated inflammation, glucose intolerance, insulin resistance through repressing Krüppel-like factor 4 (KLF4) expression." (PMID 35563728, 2022). "Regulation of the genes SIRT1 and klf4 may serve as a mechanism through which miR-34a promotes obesity associated neurodegenerative disorders, implicating its importance as a biomarker." (PMID 34690698, 2021). "Therefore, present study was to disclose the role of renal KLF4 in dietary‐induced renal injuries and underlying mechanisms in obesity." (PMID 31800161, 2020). "For SOCS3, CISH, PIM3 (Pim-3 proto-oncogene, serine/threonine kinase), and KLF4 (Kruppel-like factor 4), obesity was associated with decreased methylation and increased gene expression, while for HRASLS2, obesity was associated with decreased methylation and decreased gene expression." (PMID 29312471, 2018). "Because miR-34a significantly represses klf4, mice with increased miR-34a expression experienced significantly increased transition to the pro-inflammatory M1 macrophage type, exacerbating the systemic inflammation and metabolic dysregulation, strongly associated with obesity." (PMID 34690698, 2021). "Multiple studies have shown that berberine prevents heart disease, controls cardiac remodeling, and ameliorates KLF4-dependent obesity-related cardiac damage." (PMID 38516000, 2024). "Systemic inflammation, as well as a shift in polarization of adipose-resident macrophages from the M1 to M2 phenotype via inhibition of Krüppel-like factor 4 (Klf4) expression, leads to obesity-induced glucose intolerance and insulin resistance." (PMID 38668382, 2024). "It has been well established that KLF4 regulates macrophage polarization and plays a role in obesity." (PMID 37334370, 2023). "Mice with myeloid-specific KLF4 deletions tended to express diet-induced obesity, glucose intolerance, and insulin resistance." (PMID 36276968, 2022). "Obesity upregulated the expression of Klf2, Klf4, Klf6 and Klf9 at all timepoints in heart art, cap and ven ECs." (PMID 36400935, 2022). "Another group reported that miR-34a contained in adipocyte-derived exosomes suppressed M2 phase macrophage polarization in obesity-induced adipose tissues via downregulation of Krüppel-like factor 4 (Klf4)." (PMID 33498928, 2021). "Then, expression of Krüppel-like factor 4 (Klf4) and the polarization of M2 were both repressed, thereby exacerbating metabolic dysregulation and obesity-induced inflammation." (PMID 34703651, 2021). "Here, present study found KLF4 participated in the process of obesity‐related renal injuries partially through modulating mitochondrial function." (PMID 31800161, 2020). "Mechanistically, KLF4 maintained renal mitochondrial biogenesis and activities to combat obesity‐induced mitochondrial dysfunction." (PMID 31800161, 2020). "More importantly, we initially demonstrated that KLF4 also participated in the process of obesity‐related renal inflammation via down‐regulating NF‐κB activity." (PMID 31800161, 2020). "Through utilizing high‐fat diet‐fed mice and human renal biopsies, we provided the physiological roles of KLF4 in protecting against obesity‐related nephropathy." (PMID 31800161, 2020).
Obesity (continued). "In conclusions, decreased renal KLF4 level was important indicator for obesity‐related nephropathy, whereas genetic overexpression of KLF4 effectively improved renal function partially through up‐regulation of mitochondrial biogenesis and activities." (PMID 31800161, 2020). "In conclusions, the present findings firstly supported that renal KLF4 played an important role in combating obesity‐related nephropathy, and KLF4/mitochondrial function partially determined the energy homeostasis in chronic kidney diseases." (PMID 31800161, 2020). "Myeloid-specific Klf4 deletion augments HFD-induced obesity, insulin resistance and adipose tissue inflammation, which is indicative of the systemic metabolic impact of KLF4-dependent regulation of macrophage activation." (PMID 29942807, 2018). "Since mice lacking vesicular GABA transporter in AgRP neurons are lean and resistant to obesity, we initially expected that the over-expression of KLF4 would increase the synthesis and/or transport of GABA." (PMID 24944903, 2014). "Inhibiting MiR-34a may be a future therapeutic approach, as adipocyte-to-macrophage delivery of MiR-34a inhibits Kruppel-like factor 4 (KLF4) expression, preventing M2 polarization and promoting obesity-induced insulin resistance." (PMID 41472730, 2025). "Moreover, studies have also found that miR-34a secreted by adipocytes can inhibit M2 polarization by inhibiting the expression of Kruppel-like factor 4 (Klf4), thus promoting obesity-induced inflammation." (PMID 38660308, 2024). "KLF4 was proven to be one of potential therapeutic targets for obesity-induced cardiac injuries." (PMID 37174466, 2023). "Furthermore, the study demonstrated that high levels of miR-34a in adipose tissue increased obesity-induced inflammation by regulating Krüppel-like factor 4 (klf4)." (PMID 34690698, 2021). "High AMD1 level could promote SRY‐box transcription factor 2 (SOX2), Kruppel like factor 4 (KLF4), and NANOG expression of HCC cells through obesity–associated protein (FTO)‐mediated mRNA demethylation." (PMID 33783988, 2021). "Furthermore, DNMTs are increased in WAT in patients with obesity, thereby inducing the methylation rate of the promoter region of the Krüppel-like factor 4 (KLF4) gene (an anti-inflammatory factor) and suppressing this expression." (PMID 34199596, 2021). "We speculate based on these results that the role of KLF4 in obesity may change with age." (PMID 36276968, 2022). "Therefore, renal KLF4/mitochondrial regulation pathway could explain the pathophysiological changes in obesity‐related nephropathy and was a potential therapeutic target for chronic kidney diseases." (PMID 31800161, 2020). "Thus, our study intends to evaluate the mRNA expression level of A2bAR, KLF4/KLF15, and key inflammation signaling pathway genes in visceral adipose tissue from Uygur population to investigate the correlation of A2bAR and KLF4/KLF15 with obesity-dyslipidemia induced inflammation in Uygur population." (PMID 27199507, 2016). "We consider this result interesting, because we recently showed that Klf-4 expression in hASCs seems to be related to the cell proliferation, clonogenic ability, and differentiative potential, and to be downregulated by the pathologic condition (obesity) of patients from which cells were isolated." (PMID 24330736, 2013). "Our analysis of clinical datasets reveals that ANGPTL4 and KLF4 expression are significantly elevated in TNBC patients, particularly those with obesity, and correlates with poor prognosis." (PMID 40616161, 2025). "The novel regulator of macrophage polarization Kruppel-like factor 4 (KLF4) also controls adipogenesis, while IRF3 plays an important role in the regulation of insulin sensitivity, inflammation, and obesity." (PMID 35456006, 2022). "On the basis of obesity model, we investigated the mRNA expression levels of TLR9/KLF4 and downstream inflammatory-related factors." (PMID 30662369, 2018).
Obesity (continued). "Due to the important role of FFA in obesity-induced inflammation, we then investigated the FFA effects on TLR9/KLF4." (PMID 30662369, 2018). "Additionally, genes involved in white fat differentiation and adipogenesis pathways were downregulated by OJ consumption, including KLF4 (−2.3), RIPK1 (−1.7), PLIN2 (−1.99), and CXCL8 (−34.43); genes found as overexpressed in obesity." (PMID 41169019, 2025). "In a mouse model of dietary obesity induced by STC nutrition and a high-fat diet (HFD), miR-34a of adipocyte-secreted exosomal vesicles led to obesity-induced metabolic dysfunction and M2 macrophage proliferation by inhibiting KLF4." (PMID 35884901, 2022). "In summary, our research has explored the molecular mechanism of the inhibition effect of TLR9/KLF4 on FFA-induced inflammatory response of adipocytes, which can help to elucidate the molecular mechanism of obesity initiating inflammation and to provide a new experimental basis." (PMID 30662369, 2018). "Above all, our findings suggest that, in obese status, the lower expression level of A2bAR, KLF4, and KLF15 of visceral adipose tissue may correlate with obesity-dyslipidemia induced inflammation in Uygur population." (PMID 27199507, 2016). "The mRNA expression profile chip analysis by our previous research has demonstrated that mRNA expression levels of KLF4 and KLF15 were significantly decreased in subjects with obesity, suggesting these genes may play an important role in lipid metabolism in Uygur population." (PMID 27199507, 2016).
glioblastoma (37 papers, 2014 to 2025). The most malignant astrocytic tumor (WHO grade IV). "Additionally, SRC-1 was shown to elevate glioblastoma stemness by modulating the XIST/miR-152/KLF4 axis, which provided a new diagnostic and therapeutic biomarker for glioblastomas." (PMID 34930117, 2021). "In a model of glioblastoma, where KLF4 was inducible, the issue of the binding to highly-methylated enhancers was addressed." (PMID 39135777, 2024). "Hypoxia-inducible factor (HIF) induces the expression of both SOX2 and KLF4 in glioblastoma (GBM), which in turn upregulate CD133/15, ultimately promoting stemness expression." (PMID 38331879, 2024). "In contrast, KLF4 promotes the tumor progression in squamous cell carcinoma of the head and neck, osteosarcoma, and glioblastoma." (PMID 37031197, 2023). "Sp1 and Klf4, both main regulators of metabolism in glioblastoma, were the highest-ranking transcription factors whose motifs were enriched in all DEGs, but in particular in the shared downregulated genes." (PMID 35565433, 2022). "KLF4 is higher expressed in mesenchymal, type B, glioblastoma cultures and was here found to act as a SOX2 antagonist." (PMID 34021259, 2021). "miR-1 is markedly downregulated in glioblastomas as compared to normal brain and, despite its interaction with KLF4, restoration of miR-1 has been proposed as a therapeutic modality." (PMID 32258065, 2020). "KLF4 also acts as an oncogene in Glioblastoma by supporting glioblastoma stem cells survival and promoting their proliferation." (PMID 33233861, 2020). "Other embryonic stem cell factors such as OCT4, SOX2, MYC, and KLF4 are also found differentially expressed in glioblastoma and normal neural stem cells." (PMID 33182324, 2020). "In glioblastoma cells, KLF4 could bind to methylated DNA in cis-regulatory regions of the targets genes which induced mitochondrial morphology changes." (PMID 40265156, 2025). "KLF4 normally binds and activates the Gal-3 promoter in glioblastoma stem cells." (PMID 40566589, 2025). "Overexpression of miR-152 in glioblastoma stem cells reduced cell proliferation, migration, and invasion, but enhanced apoptosis by downregulating Krüppel-like factor 4 (KLF4) protein expression, which leads to inhibition of Gal-3 expression and MEK1/2 and PI3K signaling." (PMID 40566589, 2025). "However, KLF4 can alter the cells cycle processes through G2/M phase arrest, protect cells from nutrient deprivation-induced death, and promote the development of glioblastoma." (PMID 37031197, 2023). "In glioblastoma, KLF4 methylation-dependent transcriptional activation of UDP-glucose 6-dehydrogenase (UGDH) increases the synthesis of glycosaminoglycans (GAGs), which constitute essential structural polymers/components of the extracellular matrix (ECM), thus facilitating tumor growth and invasion." (PMID 37835497, 2023). "In summary, HIF1α and HIF2α regulate glioblastoma malignant progression through the EGFR–PI3K/AKT pathway via a positive feedback mechanism under the effects of Sox2 and Klf4, which provides a new tumour development model and strategy for glioblastoma treatment." (PMID 33762574, 2021). "MiR-7-5p is a fascinating miRNA that plays diverse roles in tumor suppression; it inhibits the invasion abilities of tumor cells by directly targeting PI3K/Akt, FAK, and KLF4 expression and may be a useful therapeutic target for the diagnosis and treatment of patients with glioblastoma." (PMID 35211545, 2022). "However, in glioblastoma KLF4 expression appears negatively correlated with SOX2 expression." (PMID 34021259, 2021). "KLF4 has also been shown to be upregulated in high-grade brain tumors, such as glioblastoma (GBM), the most aggressive and lethal adult brain tumor." (PMID 28553926, 2017). "Actually, factors secreted by glioblastoma cells activate aryl hydrocarbon receptor (AHR) in TAMs; activation of AHR, in turn, enhances the expression of the Krüppel-like factor 4 (KLF4), and suppresses NF-κB signaling by TAMs." (PMID 39194524, 2024).
glioblastoma (continued). "Prolonged hypoxia exposure (i.e., 1% O2 for a period of 72 h) stimulated glioblastoma cells to express CD133 and the stemness markers Kruppel-like factor 4 (KLF4) and SOX2 via a hypoxia inducible factor (HIF)-1α-dependent mechanism." (PMID 38532366, 2024). "The pluripotency transcription factors OCT3/4, SOX2, KLF4, and c-MYC (OSKM) result downregulated upon miRNA cluster induction and, together with POU3F2, SALL2 and OLIG2, are required for the maintenance of glioblastoma stem-like tumor propagating cells." (PMID 39135777, 2024). "In glioblastoma (GBM), overexpression of miR-152 reduced glioblastoma stem cell proliferation, migration, and invasion, as well as induced apoptosis via targeting Krüppel-like factor 4 (KLF4)." (PMID 34680020, 2021). "With regard to previous observations of an active PDGFRA signaling loop in glioblastoma we here experimentally show this can be maintained by SOX2, and subsequently turned off by SFRP2, potentially acting via KLF4." (PMID 34021259, 2021). "The Cancer Genome Atlas and Ivy Glioblastoma Atlas Project data demonstrated that IL-8 transcript expression is negatively correlated with GBM patient survival (p = 0.001) and positively correlated with that of genes associated with the GIC phenotypes, such as KLF4, c-Myc, and HIF2α (p < 0.001)." (PMID 30926789, 2019). "Our research indicated that either suppressing miR-381 or enhancing NEFL expression sensitizes glioblastoma cells to TMZ by inhibiting stemness factors (ALDH1, CD44, CKIT, KLF4, Nanog, Nestin, and SOX2)." (PMID 25605243, 2015). "The team demonstrated that SRC-1 could promote the stemness of glioblastoma cells, possibly through the X-inactive specific transcript (XIST)/mi-152 axis, promoting the expression of Kruppel-like factor 4 (KLF4)." (PMID 38553750, 2024). "Mesenchymal-like cancers, such as uveal melanoma (UVM), uterine carcinosarcoma (UCS), glioblastoma (GBM), and low-grade glioma (LGG), tend to have lower KLF4 expressions." (PMID 34680284, 2021). "Cells expressing proteins including SOX2, OCT4, pSTAT3, KLF4, NANOG, and SALL4 were identified as CSCs in Glioblastoma multiforme (GBM)." (PMID 33799834, 2021). "However, the relationship between VEGFA and KLF4 genes have no statistical significance in glioblastoma." (PMID 31198634, 2019). "This work presents SFRP2 and SOX2 as counteracting inducers of gene expression based glioblastoma subtypes, where SFRP2 suppresses SOX2 via non-canonical WNT signaling, KLF4, PDGFRs, and AKT." (PMID 34021259, 2021).